PRMT5 (protein arginine methyltransferase 5)
Diseases named in the same sentence as PRMT5 in open-access papers (continued):
Sharing a sentence is not in itself a finding about the gene and the disease.
lung carcinoma (continued). "PRMT5 expression is elevated in lung cancer, and the TGFβ–PRMT5–MEP50 axis regulates cancer cell invasion through histone H3 and H4 arginine methylation, which couples transcriptional activation and repression." (PMID 35111150, 2021). "Selective small molecules PRMT5 inhibitors were also explored recently for anti-lung cancer activity." (PMID 34200178, 2021). "PRMT5 promotes the apoptosis of lung cancer cells through Akt/Gsk3β signaling induced by resveratrol." (PMID 33650320, 2021). "In human lung cancers, cytoplasmic localization of PRMT5 was found to correlate with high-grade tumors, whereas PRMT5 nuclear localization was more frequent in well-differentiated carcinoid tumors." (PMID 33989303, 2021). "Collectively, our findings illustrate that PRMT5 contributes to human lung cancer cell proliferation and migration via modulating STAT3 signaling." (PMID 34026434, 2021). "We constructed a stable system to downregulate PRMT5 in NCI-H460 human lung cancer lines to determine the oncogenic properties of PRMT5." (PMID 35111150, 2021). "Particularly, PRMT5-mediated increased FGFR3 signaling is caused by silencing of the miR-99 family, which negatively regulates the expression of FGFR3 in lung cancer." (PMID 34685445, 2021). "Accumulating evidence has shown that PRMT5 is the ectopic expression in many types of human cancer and regulates cell metabolism, including lung cancer, pancreatic cancer, breast cancer, leukemia, lymphoma, glioblastoma, prostate cancer, and bladder cancer." (PMID 33495409, 2021). "PRMT5 promotes human lung cancer cell proliferation via direct interaction and regulation of AKT activation." (PMID 34522186, 2021). "A recent study has been reported that PRMT5 co-localizes with Akt and regulates Akt activation, which accelerates human lung cancer cell growth." (PMID 33495409, 2021). "Overall, our results demonstrate that PRMT5 inhibition alone inhibited lung cancer progression but induced PD-L1 expression that compromised the antitumor activity of CD8+ T cells." (PMID 35111150, 2021). "The findings of the current study indicate that PRMT5 inhibition using AMI-1 has an additive effect on the antineoplastic activity of cisplatin in lung cancer cells." (PMID 34200178, 2021). "Similar results were also generated for circRNA PRMT5 (circ-PRMT5); high expression levels indicated lung cancer patients were more likely to develop poor progression-free survival (PFS) and OS." (PMID 34295810, 2021). "Altogether, our results showed a potential antineoplastic activity of PRMT5 inhibitor in lung cancer cells in combination with cisplatin." (PMID 34200178, 2021). "We also provided strong evidence for the essential partnership between PRMT5 inhibition and anti-PD-L1 therapy in lung cancer to improve treatment efficacy." (PMID 35111150, 2021). "Protein arginine methyltransferase 5 (PRMT5) is associated with the development of many types of cancers and tumors, especially lung cancer." (PMID 33650320, 2021). "Ectopic expression of PRMT5 or MEP50 in A549 lung cancer cells dose-dependently inhibited TGFBR2 promoter reporter activity." (PMID 33995678, 2021). "PRMT5 has also been shown to accelerate lung cancer progression and metastasis via the histone methylation of the miR-99 family and in turn, activating the Erk1/2 and Akt pathway through FGFR3 signaling." (PMID 34200178, 2021). "Immunohistochemical (IHC) analysis of tissue microarray of nonsmall cell lung cancer (NSCLC) showed that PRMT5 is markedly overexpressed in cancer cells compared to adjacent normal tissues." (PMID 34026434, 2021). "Analysis of the proximal PRMT5 promoter identified CAATT boxes that are recognized by the transcription factor NF-Y and can induce PRMT5 transcription in prostate and lung cancer lines." (PMID 32743345, 2020). "In lung cancer, PRMT5 activity increases FGFR3 expression by repressing miR-99, and in AML (acute myeloid leukemia) PRMT5 repression of miR-29b upregulates FLT3." (PMID 32743345, 2020).
lung carcinoma (continued). "We also demonstrated that PRMT1 and PRMT5 had opposing effects on chemotherapeutic agent-mediated apoptosis in lung cancer cells." (PMID 30736843, 2019). "Silencing PRMT5 or blocking PRMT5 activity prevented lung cancer cell growth and proliferation through induction of cell cycle arrest." (PMID 30461193, 2019). "Taken together, these results suggest that blocking PRMT5 activity can prevent lung cancer cell proliferation and cell cycle progression." (PMID 30461193, 2019). "PRMT5 expression level was markedly up‐regulated in lung cancer tissues compared with normal tissues." (PMID 30461193, 2019). "Our findings raise the possibility that PRMT5 promotes human lung cancer cell proliferation via direct interaction and regulation of Akt activation." (PMID 30461193, 2019). "Our findings suggest that PRMT5 is a key regulator for human lung cancer cell proliferation and identifying PRMT5 downstream targets will aid in illustrating the role of PRMT5 in human lung cancer development." (PMID 30461193, 2019). "To investigate the functions of PRMT5 in human lung cancer, we firstly examined the PRMT5 protein expression level in different human lung cancer cell lines." (PMID 30461193, 2019). "This phenomenon was further assessed in the analysis of human lung cancer tissues, in which we detected ectopic expression level of PRMT5 in human lung cancer tissues and very low expression level of PRMT5 in adjacent lung tissues." (PMID 30461193, 2019). "Altogether, our results indicate that PRMT5 promotes human lung cancer cell proliferation through direct interaction with Akt and regulation of Akt activity." (PMID 30461193, 2019). "All these observations indicate that PRMT5 promotes human lung cancer cells proliferation by interaction with Akt and regulation of Akt kinase activity, which further lead to the activation or inhibition of key downstream targets of Akt by phosphorylation." (PMID 30461193, 2019). "Taken together, these results imply that PRMT5 plays a pivotal role in human lung cancer progression." (PMID 30461193, 2019). "In summary, our results revealed that PRMT5 was frequently overexpressed in human lung cancer cells and tissues." (PMID 30461193, 2019). "Our findings not only validate that PRMT5 regulates cells proliferation via control of cell cycle, but also indicate that PRMT5 is a key regulator for human lung cancer cell growth." (PMID 30461193, 2019). "PRMT5 plays an important role in cancer cell growth and proliferation, especially in human lung cancer cells." (PMID 30461193, 2019). "More importantly, the new insights into the activation of Akt medicated by PRMT5 provide much new information for the mechanisms of carcinogenic effect of PRMT5 in human lung cancer." (PMID 30461193, 2019). "For example, PRMT5 has been reported to be frequently overexpressed and correlated with poor outcomes in lung cancer." (PMID 30922330, 2019). "In lung cancer, PRMT5 has been reported to regulate the HIF1 signaling pathway, but its direct roles in aerobic glycolysis under the control of the HIF1 signaling pathway have seldom been reported." (PMID 30922330, 2019). "In this study, our results revealed that PRMT5 was overexpressed in human lung cancer cell lines and human lung cancer tissues." (PMID 30461193, 2019). "We overexpressed PRMT5 in lung cancer cells for 24 h and then treated the cells with 2 μmol/L doxorubicin for 24 h." (PMID 30736843, 2019). "In order to further confirm our results, the human lung cancer tissues and adjacent normal tissues were used to detect PRMT5 mRNA and protein expression level." (PMID 30461193, 2019). "Collectively, these results demonstrate that PRMT5 promotes lung cancer cell proliferation through regulation of Akt activity, but not PTEN and mTOR signalling pathway." (PMID 30461193, 2019).
lung carcinoma (continued). "By analyzing the GEO database, we found that the level of BTG2 was significantly upregulated in several cancers, including lung cancer and prostate cancer, after PRMT5 knockdown." (PMID 29441724, 2018). "An increasing number of studies emphasized that PRMT5 was upregulated in lymphomas, breast cancer, lung cancer, colorectal cancer, and glioblastoma." (PMID 29545752, 2018). "As the relationship of PRMT5 and lung cancer is constantly revealed, it is urgent to search for effective inhibitors targeting PRMT5 for lung cancer therapy." (PMID 29545752, 2018). "Previous studies used RNA interference technologies revealed an essential role PRMT5 in growth of lung cancer cells and lung tumor xenografts." (PMID 28806746, 2017). "The importance of PRMT5 in cancer is demonstrated by its upregulation in several human malignancies and essential role in growth of lung cancer cells and tumor xenografts." (PMID 28806746, 2017). "PRMT5 is upregulated in various types of cancers, including but not limited to pancreas, colon, breast, prostate, and lung cancers, as well as lymphoma and melanoma." (PMID 28591716, 2017). "Since the invasive phenotypes, metastasis-related gene expression and PRMT5-dependent histone PTM of lung cancer cells were directly dependent on SHARPIN-PRMT5, this interaction likely alters the transcriptional outcomes by targeting histones." (PMID 28903384, 2017). "Overexpression of PRMT5 has been found in many kinds of tumours, including leukaemia 15, lymphoma 16, lung cancer 17, colorectal cancer 18 and breast cancer." (PMID 27860244, 2017). "We identified a set of genes whose expression was altered by silencing PRMT5 expression in lung cancer A549 cells." (PMID 28806746, 2017). "Meanwhile, compared to normal lung cells, lung cancer cells displayed much higher levels of PRMT5 RNA and protein." (PMID 28903384, 2017). "We have shown in this report that identified PRMT5-inhibitors inhibited growth of lung cancer cells in tissue culture and oral administration of compound C9a suppressed growth of lung tumor xenografts." (PMID 28806746, 2017). "Silencing PRMT5 expression inhibited growth of lung cancer cells by suppressing cellular proliferation and arrested the cell cycle at the G1 phase." (PMID 28806746, 2017). "It has been demonstrated that PRMT5 and its enzymatic activity are required for growth of lung cancer cells." (PMID 28806746, 2017). "As expected, the C9 analogue (C9a) inhibited PRMT5 activity and growth of lung cancer cells with higher efficacy and has improved oral drug availability compared to C9." (PMID 28806746, 2017). "This study reveals a novel pathway that PRMT5/WDR77 regulates GLIPR1 expression to control lung cancer cell growth and GLIPR1 as a potential therapeutic agent for lung cancer." (PMID 26988096, 2016). "Silencing WDR77 or PRMT5 expression in lung cancer A549 cells induced expression of GLPIR1 revealed by DNA microarray (GSE56757) and RT-PCR analyses." (PMID 26988096, 2016). "More important, PRMT5 and p44 are re-expressed in lung cancers and the shRNA-mediated silencing of PRMT5 or p44 expression strongly inhibited proliferation of lung cancer cells in tissue culture and abolished growth of lung tumor xenografts in nude mice." (PMID 27480244, 2016). "Infection of lung cancer A549 cells with lentivirus expressing PRMT5 or p44 small hairpin RNA (shRNA) resulted in 94 % or 83 % reduction in PRMT5 or p44 mRNA levels, respectively." (PMID 27480244, 2016). "PRMT5 and p44 are highly expressed in prostate and lung cancers and are essential for growth of cancer cells." (PMID 27480244, 2016). "In contrast, lung cancer samples express high levels of PRMT5, WDR77, ErbB2, ErbB3 and FGFR3 and decreased levels of GLIPR1, Leprel1 and BTG2." (PMID 27480244, 2016). "Quantitative real-time polymerase chain reaction, Western immunoblot and immunohistochemistry were used to characterize PRMT5 expression in lung cancer cell lines and human tumors." (PMID 24326178, 2013).
lung carcinoma (continued). "Increased protein levels of PRMT5 have been observed in leukemia, lymphoma, glioma, ovarian, breast, prostate, and lung cancer." (PMID 24098663, 2013). "The overexpression of PRMT5 has been found in hematological and epithelial malignancies including lymphoma, prostate and lung cancer cell lines." (PMID 24326178, 2013). "Cytoplasmic and nuclear expression of PRMT5 was identified in 5 of 5 lung carcinoma cell lines, including NSCLC (NCI-H1299), ADC (NCI-A549), SQC (NCI-H520), and SCLC (NCI-H69 and NCI-H719)." (PMID 24326178, 2013). "Analysis of PRMT1 and PRMT5 transcript expression using the R2 platform focusing on the Filion dataset of sarcomas that includes Ewing sarcoma patients alongside other fusion-positive sarcomas and breast and lung cancer datasets." (PMID 40823091, 2025). "Similarly, in lung cancer, PRMT5 inhibition disrupts the HIF-1α/VEGFR/AKT/eNOS axis and downstream nitric oxide production, thereby impairing angiogenesis and EMT." (PMID 41204384, 2025). "Additionally, in lung cancer, PRMT5 suppresses miR-99 through H4R3me2s, upregulating FGFR3 and activating ERK1/2 and AKT pathways to promote tumor progression." (PMID 41204384, 2025). "Furthermore, another study revealed that PRMT5 inhibition by GSK591 hampers the epithelial-mesenchymal transition in lung cancer cells by modulating the EGFR/Akt signaling pathway." (PMID 39826691, 2025). "Unc-51 like autophagy activating kinase 1 (ULK1), a key regulator of autophagy in lung cancer cells, is methylated by overexpressed PRMT5, enhancing the autophagic process and improving the survival rate of lung cancer cells under hypoxic conditions, promoting resistance to carboplatin." (PMID 38525426, 2024). "Our study highlights the vital role of PRMT5 in the development and progression of lung cancer." (PMID 37400960, 2023). "A common PRMT dysregulation, specifically of PRMT5, has been correlated with the loss of MTAP (5-methylthioadenosine phosphorylase) expression in lung cancer, resulting in the accumulation of methylthioadenosine (MTA), which significantly inhibits PRMT5 activity." (PMID 38001653, 2023). "Nevertheless, how PRMT5 regulates lung cancer development, progression and downstream targets are largely unknown." (PMID 37461162, 2023). "Nevertheless, it is still unclear whether PRMT5 regulates angiogenesis to promote lung cancer cell metastasis, and the potential molecular mechanism remains obscure." (PMID 37400960, 2023). "Additionally, we detected the PRMT5 protein expression in lung cancer cell lines and normal human fetal lung fibroblast cells (IMR90)." (PMID 37400960, 2023). "Further studies are needed to identify more targets of PRMT5 and its functions in lung cancer." (PMID 37461162, 2023). "However, we cannot ignore the vital downstream targets of PRMT5 that mediated lung cancer development." (PMID 37461162, 2023). "By showing that PRMT5 was induced by hypoxia and participated in regulating angiogenesis, EMT, and metastasis, this study provided valuable insights into the molecular mechanisms underlying these processes in lung cancer." (PMID 37400960, 2023). "Treatment with GSK591 also blocked the methylation of KLF5 by PRMT5 in lung cancer cells." (PMID 37461162, 2023). "In addition, we found that the expression of PRMT5 was higher in lung cancer than in normal lung tissue." (PMID 36999124, 2023). "Finally, we found that inhibition or downregulation of PRMT5 resulted in repressing lung cancer cell growth both in vitro and in vivo." (PMID 37461162, 2023). "Indeed, the ubiquitination of Vimentin influenced by symmetric dimethylarginine (sDMA) is thought to be necessary for the roles of MTAP and PRMT5 in lung cancer metastasis." (PMID 36969045, 2023). "Furthermore, PRMT5 promotes the proliferation and growth of lung cancer cells, which can be inhibited by the specific PRMT5 inhibitors or shRNA both in vitro and in vivo." (PMID 37461162, 2023).
lung carcinoma (continued). "To discover whether PRMT5 interacts with KLF5 in human lung cancer cells, we used the immunoprecipitation (IP) method to detect the endogenous interaction between PRMT5 and KLF5." (PMID 37461162, 2023). "More recently, Akt kinase activity has shown to be involved in PRMT5 export from the nucleus in lung cancer cells, although the mechanism remains unknown." (PMID 37458145, 2023). "Finally, inhibition of PRMT5 by GSK591 suppressed lung cancer cell proliferation in a dose‐dependent manner." (PMID 37461162, 2023). "However, further research is needed to fully understand the role of PRMT5 in lung cancer under hypoxia and to develop effective treatments under this condition." (PMID 37400960, 2023). "In lung cancer, the protein arginine methyltransferase 5 (PRMT5) binds to SMAD7 and methylates it on arginine-57, enhancing the binding of SMAD7 to the IL-6 co-receptor gp130, thereby ensuring potent activation of STAT3, which in turn promotes tumour cell proliferation and progression." (PMID 37685308, 2023). "Transcriptome profiling of PRMT5/MEP50 shRNA knockdown lung cancer models identified differential expression of components of the TGFβ pathway, suggesting that PRMT5 may be important for the TGFβ response and subsequent cancer metastasis." (PMID 37795443, 2023). "Similar to its role in melanoma, SHARPIN interacts with PRMT5 in lung cancer cells." (PMID 38017534, 2023). "Our findings present solid proof of a strong association between PRMT5 and angiogenesis/EMT and imply that inhibiting PRMT5 activity could be a viable therapeutic strategy for combating lung cancer that exhibits abnormal angiogenesis." (PMID 37400960, 2023). "Our findings indicate that PRMT5 promotes lung cancer epithelial-mesenchymal transition (EMT), which might be possibly through controlling the HIF-1α/VEGFR/Akt/eNOS signaling axis." (PMID 37400960, 2023). "Collectively, our study highlights KLF5 as a new target for PRMT5 to promote lung cancer." (PMID 37461162, 2023). "The exact role of PRMT5 in controlling cancer cell metastasis, particularly in human lung cancer, remains unclear." (PMID 37400960, 2023). "Besides its importance in embryonic development, PRMT5 is also highly expressed in various cancer models, including leukemia, lymphoma, glioblastoma, lung cancer, and breast cancer." (PMID 35531958, 2022). "PRMT5 is highly expressed in human lung cancer cells and tissues." (PMID 36364261, 2022). "MTAP and PRMT5 negatively correlate with vimentin in lung cancer samples." (PMID 35766227, 2022). "Next, we used TCGA RNA-seq data of human lung adenocarcinoma and found that PRMT5 expression was much higher in lung tumor tissues compared with normal tissues, suggesting that PRMT5 may be involved in tumorigenesis in lung cancer." (PMID 35111150, 2021). "Therefore, the use of AMI-1 to inhibit PRMT5 is a promising therapeutic candidate for improving lung cancer resistance to cisplatin." (PMID 34513846, 2021). "Indeed, when PRMT5 was knocked down in lung cancer lines and cocultured with CD8 T cells in vitro, we found that the CD8 T cells exhibited reduced antitumor activity compared with control cells." (PMID 35111150, 2021). "Our findings address an unmet clinical need in which combining PRMT5 inhibition with anti-PD-L1 therapy could be a promising strategy for lung cancer treatment." (PMID 35111150, 2021). "Furthermore, targeting PRMT5 in immunocompromised mice with lung cancer resulted in reduced tumor progression; however, the treatment effect was reduced significantly in immunocompetent mice and associated with increased PD-L1 expression in the tumor tissue." (PMID 35111150, 2021). "Combining PRMT5 inhibition with anti-PD-L1 therapy synergistically inhibited the growth of lung cancer cells and activated CD8+T cell immune surveillance, which may be an effective approach for lung cancer treatment." (PMID 35111150, 2021).